WWOX (WW domain containing oxidoreductase)
Diseases named in the same sentence as WWOX in open-access papers (continued):
Sharing a sentence is not in itself a finding about the gene and the disease.
tumor (continued). "Our results indicate that WWOX, apart from its tumor-suppressor function, appears to be a key regulator of the main cellular functions of the cell cycle and apoptosis." (PMID 25051421, 2014). "WW domain-containing oxidoreductase (designated WWOX, FOR, or WOX1) is a candidate tumor suppressor." (PMID 25537520, 2014). "Supporting evidence from Drosophila and mouse knockout models has revealed that WWOX acts more than just a tumor suppressor." (PMID 25537520, 2014). "An interesting finding is that TMEM207 facilitates tumor invasion, possibly through binding to WWOX, a tumor suppressor molecule, and attenuating the tumor growth suppression activity of the molecule." (PMID 25305140, 2014). "A number of recent reports have also correlated BC development with changes in the FHIT gene which similarly to WWOX is located in a fragile site (FRA3B) and has again been linked to tumour development." (PMID 24955146, 2014). "The WW domain containing protein WWOX has been postulated to behave as a tumor suppressor in breast and other cancers." (PMID 24330518, 2013). "As a putative tumor suppressor gene, WWOX is located at chromosome 16q23.3-q24.1, spanning common fragile site FRA16D." (PMID 24330824, 2013). "WW domain-containing oxidoreductase WWOX (FOR or WOX1) is a proapoptotic protein and is considered as a tumor suppressor." (PMID 23459853, 2013). "Fragile histidine triad (FHIT) and WW-domain oxidoreductase (WWOX) are tumor suppressor genes that encompass the two most active common fragile sites." (PMID 24137446, 2013). "Western blot analysis showed the expression level of WWOX protein in the tumor issue of the nude mice in the experimental group to be 0.65±0.031, while that of the control group was 0.25±0.047." (PMID 24137423, 2013). "The putative role of WWOX as a tumor suppressor has been suggested by various studies observing suppressed in vivo tumorigenicity of human cancer cells when WWOX was ectopically overexpressed." (PMID 22574198, 2012). "We are interested in understanding the normal and putative tumor-suppressive functions of WWOX in more detail." (PMID 22574198, 2012). "The function of WWOX as a tumor suppressor was later supported by in vivo evidence that inactivation of WWOX gene accelerates tumor progression in mice and that WWOX is haploinsufficient for the initiation of tumor development." (PMID 23109895, 2012). "The WW domain-containing oxidoreductase (WWOX) gene was identified as a potential tumor suppressor gene mapping to chromosomal region 16q23." (PMID 22574198, 2012). "MSS tumors have significantly more CNAs than microsatellite-instable (MSI) tumors: within the MSI tumors a novel deletion of the tumor suppressor WWOX at 16 q23.1 was identified (p<0.01)." (PMID 22860045, 2012). "FHIT and WWOX (the genes located within FRA3B and FRA16D respectively) have both been shown to function as tumour suppressors genes, and their inactivation have been associated with a poor clinical prognosis in cancer." (PMID 23675233, 2011). "The FHIT gene is often involved in deletions which map specifically to the fragile site region in various types of cancer, and deletion of WWOX is also frequently observed in tumor cells." (PMID 21286310, 2010). "In response to DNA damage, it has been shown that WWOX, a recently introduced tumor suppressor, can be activated." (PMID 22615609, 2010). "In year 2000, we and two other groups have independently discovered a candidate tumor suppressor, named WW domain-containing oxidoreductase (design-nated WWOX, FOR, or WOX1) [1-7; reviews]." (PMID 21212468, 2010). "The two most highly breakable fragile sites, FRA3B and FRA16D, lie within the tumor suppressor genes FHIT and WWOX, respectively." (PMID 21286310, 2010).
tumor (continued). "Recent studies have shown that the WW1 domain of the WWOX protein has an essential function in its tumour suppressor function by regulating the subcellular localisation of p73 and AP-2γ, both of which contain the proline-rich ligand ‘PPXY’ motif." (PMID 19352382, 2009). "WW domain-containing oxidoreductase (WWOX) was cloned and identified as a potential tumor suppressor gene mapping to the chromosome region 16q23." (PMID 19936220, 2009). "The role of WWOX as a tumor suppressor is supported by in vitro studies with human cancer cells and in vivo studies using mouse models." (PMID 19936220, 2009). "Several studies reported that ectopic WWOX expression suppressed the in vivo tumorigenicity of various human tumor types including, breast, lung, prostate and ovarian cancer cells when xenografted in nude mice." (PMID 19936220, 2009). "This is in stark contrast with Watanabe (2003) who observed that some cells of normal and tumor breast and gastric cases had WWOX protein expression localized to the nuclei." (PMID 15982416, 2005). "Normal ovarian tissues displayed a consistently strong WWOX specific signal while WWOX protein expression levels were extremely variable among tumor samples." (PMID 15982416, 2005). "The putative tumor suppressor WWOX gene spans the common chromosomal fragile site 16D (FRA16D) at chromosome area 16q23.3-24.1." (PMID 15982416, 2005). "WWOX (WW-domain containing oxidoreductase), a candidate tumour suppressor gene, spans over 1 Mb of DNA at 16q23.3–24.1, the location of FRA16D, the second most active FS in human genome." (PMID 15266310, 2004). "The interest in the WWOX gene is due to its chromosomal location and potential tumour suppressor activity." (PMID 15266310, 2004). "The WWOX (WW-domain containing oxidoreductase) is a candidate tumour suppressor gene spanning the same chromosome region, 16q23, as the second most common fragile site (FS), FRA16D." (PMID 15266310, 2004). "C1q has an anti-tumor role through the WWOX oncogene in breast and colon cancers." (PMID 40370471, 2025). "Here, WWOX acts as a tumor suppressor by directly interacting with RUNX2." (PMID 41141138, 2025). "This study concludes that RUNX2 is markedly overexpressed in ES tissues and may contribute to tumor advancement, whereas WWOX levels remain stable." (PMID 41141138, 2025). "WWOX acts as a tumor suppressor and plays a role in apoptosis." (PMID 38886371, 2024). "Although there has been information reported on the relationship between WWOX protein deficiency and cancer development, the tumor suppressor function of WWOX has not yet been fully elucidated." (PMID 39473747, 2024). "As mentioned, WWOX is involved in PCa tumorigenesis and tumor 17-20." (PMID 37324196, 2023). "Lastly, in HCC, we found coprecipitation of protein COTE1 and WWOX, a classical tumor suppressor which was also lost/reduced expression in ICC; whether the similar phenomenon exists in ICC cells is still uncertain." (PMID 37780485, 2023). "WWOX/TFAP2A demonstrates anti-tumor functions, while WWOX/TFAP2C still promotes oncogenesis." (PMID 37291585, 2023). "Different in vitro and in vivo functional studies have indicated WWOX’s role as a tumor suppressor." (PMID 37974179, 2023). "Our findings revealed that WWOX acts as a barrier to halt tumor progression." (PMID 36572673, 2022). "The WW domain-containing oxidoreductase (WWOX) gene has been reported to be a tumor suppressor." (PMID 36364214, 2022). "The diverse signaling is an example of what underlies the heterogeneity; thus, the aim of this research was to use three BLCA cell lines as biological replicates in an attempt to investigate the influence of WWOX, AP-2α and AP-2γ on the signal transduction in this tumor." (PMID 35563688, 2022).
tumor (continued). "In addition to typical tumor suppressor functionalities related to proliferation or invasion, WWOX-related metabolic changes have been observed in many different cancers." (PMID 36271927, 2022). "Indeed, PDX139 with WWOX overexpression resulted in smaller and lighter tumors compared to PDX139 WT and PDX139 EV, further confirming WWOX tumor suppressor activity." (PMID 36572673, 2022). "The findings indicate that WWOX and AP-2α behave as tumor suppressors and may act synergistically while AP-2γ is an oncogene that can be guided by WWOX against tumor progression." (PMID 35563688, 2022). "Notably, the tumor suppressor function of WWOX is dependent on the expression level of GRP78 in ovarian cancer cells." (PMID 35047994, 2021). "WWOX loss would therefore contribute to the progression of carcinogenesis rather than the initiation of the tumor." (PMID 33946771, 2021). "The nature of this variant apparently results from tumor suppressor synergism compared to WWOX or AP-2α overexpression alone: i.e. processes that are not regulated by WWOX itself are manifested by AP-2α and vice versa." (PMID 33718178, 2021). "Therefore, an in silico analysis was also performed on clinical data obtained from TCGA database since the tumor profile is changing globally in terms of WWOX and TFAP2C levels which corresponded to our research model." (PMID 33691672, 2021). "Thirdly, mouse models also shed light on the tumor suppressor activity of WWOX." (PMID 33946771, 2021). "The WWOX gene was initially cloned as a putative tumor suppressor." (PMID 34747138, 2021). "Secondly, the ability of WWOX to inhibit proliferation, support-dependent growth, migration, invasion, tumor growth, and metastasis of many different cell lines has been reported, which is consistent with tumor suppressive activity." (PMID 33946771, 2021). "It is interesting to note that some of the most common CFSs, such as FRA3B and FRA16D, are encompassed by FHIT and WWOX tumor suppressor genes, respectively, suggesting that breaks at these genes could infer positive selection and growth advantage." (PMID 32785139, 2020). "WWOX is a well-known tumour suppressor that affects genetic instability, apoptosis and growth." (PMID 33113804, 2020). "However, when in combination, Zfra4-10 and WWOX7-21 reduced the binding of WWOX with target proteins and allowed tumor growth in vivo." (PMID 32764489, 2020). "Importantly, in vivo studies investigating the phenotypic consequences of global Wwox deletion found an increased incidence of spontaneous tumor formation in mice, suggesting a critical role for WWOX in tumorigenesis." (PMID 33129329, 2020). "Nevertheless, the finding that WWOX expression is frequently decreased in histologically high-grade tumors merits further investigation as to the role of WWOX in promoting an aggressive tumor phenotype." (PMID 33129329, 2020). "Under similar experimental conditions, antiserum against WWOX at pY33 or pY287, along with Hyal-2 antiserum, reduced the BCC tumor growth in T/B-deficient NOD-SCID mice (30 to 50% reduction), suggesting that Zfra inhibits WWOX phosphorylation at Tyr33, which is needed for suppressing cancer growth." (PMID 32764489, 2020). "Although loss of WWOX is correlated with cancer development and progression, it does not behave as a highly penetrant classical tumor suppressor in most mouse models." (PMID 31275852, 2019). "WW domain-containing oxidoreductase (Wwox) is a putative tumor suppressor." (PMID 31340538, 2019). "Recent advances suggest another molecular mechanism that could abrogate the tumor suppressor function of WWOX." (PMID 30214895, 2018). "We speculate that the aberrant expression of TMEM207 might be an early event during oral carcinogenesis, wherein cytoplasmic TMEM207 binds to WWOX to attenuate the tumour suppressor function of the latter in invasive squamous cells." (PMID 29164763, 2018). "Several studies have suggested that the WWOX gene functions as a tumor suppressor in liver cancer." (PMID 29724996, 2018).
tumor (continued). "WWOX is believed to exert its tumour suppressor role via binding to various molecules." (PMID 29164763, 2018). "How is the tumor suppressor function of WWOX impaired in cancer cells?" (PMID 30214895, 2018). "We propose that highly expressed TMEM207 may competitively bind to the WW domain of WWOX, thus inhibiting the tumor suppressor function of WWOX during carcinogenesis in digestive tract cancers." (PMID 30214895, 2018). "Furthermore, a number of Wwox mutant mouse models have also suggested tumor suppressive roles for WWOX." (PMID 30082886, 2018). "Although further studies are required, TMEM207 and other members of the STMC6 family may constitute a novel transmembrane protein family that hinder the WWOX tumor suppressor function." (PMID 30214895, 2018). "WWOX was significantly down regulated (p = 0.000005) in OS tumor samples compared to controls." (PMID 29152092, 2017). "The results shown that WWOX is a bona fide tumor suppressor." (PMID 28426730, 2017). "Hyaluronidases PH-20, Hyal-1 and Hyal-2 induce the expression of tumor suppressor WWOX." (PMID 27845895, 2017). "WWOX (WW domain-containing oxidoreductase) is known to be an important tumor suppressor in cancer." (PMID 28977834, 2017). "Both WWOX and Smad4 are tumor suppressors and proapoptotic proteins." (PMID 27845895, 2017). "The WWOX expression also suppresses tumor growth and induces cell apoptosis." (PMID 27655721, 2016). "Because SETDB2 knockdown led to significant inhibition of cell growth, migration and invasion, we further selected six tumor- or differentiation-related genes (WWOX, CADM1/TSLC1, CCDC80, NDRG1, CA9 and FZD9) that have been reported to show altered expression in several cancers including GCs." (PMID 27572307, 2016). "Because previous studies showed that CNV-67048 influences WWOX expression in tumor tissues, considering the function and abnormal expression of WWOX in EOC, we hypothesized that the CNV-67048 contributes to EOC development." (PMID 27190995, 2016). "For example, tumor suppressor WWOX is frequently missing in cancer cells." (PMID 27999774, 2016). "WWOX is emerging as a tumor suppressor that is also involved in metabolic and neurological disorders, In vivo studies have indicated that the WWOX gene is alternatively knocked out in mice, causing Leydig cell development failure in the testis and affecting normal prostate function." (PMID 27655721, 2016). "WW domain–containing oxidoreductase (WWOX) is a tumor suppressor gene that spans FRA16D at 16q23." (PMID 27977694, 2016). "Low or undetectable expression and aberrant transcription of the WWOX gene in various cancers suggest that it may act as a tumor suppressor gene." (PMID 25612104, 2015). "Therefore, in this study we aimed to investigate the role of WWOX in HNSCC and evaluated the WWOX mutation rate and mRNA levels in HNSCC tumor tissue samples." (PMID 25612104, 2015). "Mean expression values of the WWOX gene in tumor and normal tissues." (PMID 25612104, 2015). "Tumor-suppressing functions of WWOX identify it as a master regulator that protects from genomic instability (but also having major roles in other cellular process that could not be discussed here)." (PMID 27551470, 2015). "Mouse knock-out experiments also support the tumor suppressor function of the WWOX gene." (PMID 25612104, 2015). "The results indicate that the tumor suppressor WWOX suppresses stem cell properties in cancer stem cells, including self-renewal ability, differentiation potential, in vivo tumorigenic capability, high-level expression of stem cell genes and multidrug resistance." (PMID 25789010, 2015). "WWOX behaves as a suppressor of tumor growth in some cancer lines." (PMID 24330518, 2013).
tumor (continued). "Although downregulation of tumor suppresser WWOX expression has frequently been reported in various types of cancers, Wwox deletion did not necessarily increase the proliferation or development of premalignant lesions, suggesting that WWOX is not a classical tumor suppressor gene." (PMID 27234396, 2013). "Intriguingly, the polymerizing TIAF1 increases the expression of tumor suppressors Smad4 and WWOX." (PMID 27234387, 2013). "Two tumor suppressor genes, FHIT and WWOX, are associated with FRA3B and FRA16D, respectively." (PMID 23109895, 2012). "The WWOX gene is considered to be a new tumor suppressor gene after discovery of the FHIT gene." (PMID 23276146, 2012). "Further research into effects of PAR-2 on WWOX regulation in cancer could also be interesting as the tumor suppressor gene is up-regulated by PAR-2, even though PAR-2 has been reported to induce proliferation in certain carcinomas." (PMID 21072196, 2010). "WOX2 may act as a dominant negative and counteracts the tumor suppressor function of wild type WWOX/WOX1 in vivo, thereby supporting cancer growth." (PMID 19484134, 2009). "As such, reduced WWOX expression would also attenuate apoptosis resulting from exposure to foreign environments, such as pre-metastatic sites prior to the establishment of new tumor growth." (PMID 19774227, 2009). "Simultaneous scanning of FHIT and WWOX exons in the context of early tumorigenesis and tumor progression, may help clarify the mechanistic events related to cancer development which are not revealed by imuno histochemistry assays." (PMID 16895604, 2006). "Alterations of the FHIT gene occur early in tumour development, particularly in cancers related to environmental carcinogens, raising the possibility that carcinogen-induced alterations of WWOX gene are also an early event in the process of hepatocarcinogenesis." (PMID 15266310, 2004). "Understanding the interations and pathways involved in the tumour suppressor function of WWOX may provide new targets for therapy of various cancers including HCC." (PMID 15266310, 2004). "Even though homozygous deletions/mutations completely inactivating the WWOX gene are rare, neither the hundreds of patients reported worldwide nor the parents of these children, who by definition are WWOX haploinsufficient, developed neoplasia." (PMID 33946771, 2021). "Furthermore, it has been found that WWOX recognizes the PPxY motif of ezrin, a protein that links transmembrane signaling to the reorganization of cytoskeleton, influencing cell migration and tumor progression." (PMID 34204789, 2021). "Recent studies have suggested that WWOX may act more than a tumor suppressor." (PMID 32000863, 2020). "Collectively, ITCH participates in numerous pathways, and loss of its expression causes craniofacial abnormalities hepatomegaly and severe inflammation in human; while an increased level of ITCH might otherwise enhance tumorigenesis or enhance the anti‐tumor role of WWOX." (PMID 32259050, 2020). "In addition, we suggest that ectopically expressed TMEM207 may competitively bind to the WW domain of WWOX, thus inhibiting the tumor suppressor function of WWOX during carcinogenesis in certain cancers." (PMID 31699801, 2019). "Similar to the PTEN tumor suppressor, differences in the types of neoplasias observed in these animal models might be due to the regulation of WWOX by various molecular mechanisms, including VOPP1-mediated relocation, which generates dosage-dependent WWOX functions in human cancers." (PMID 30285739, 2018). "Moreover, WWOX tumor suppressive function was questioned in different research articles." (PMID 30619734, 2018). "However, few patients harboured SVs in TOX and WWOX, indicating these genes may rarely act as tumour suppressor genes in DLBCL." (PMID 30275490, 2018).